INS (insulin)
Diseases named in the same sentence as INS in open-access papers (continued):
Sharing a sentence is not in itself a finding about the gene and the disease.
Abdominal obesity (continued). "In order to explain increased ASP levels in association with abdominal obesity, we highlight “metabolic resistance” as an important feature that may be shared between insulin and ASP." (PMID 24533222, 2013). "Men presenting with abdominal obesity had a deteriorated cardiometabolic risk profile compared to lean men as well as a more severe nocturnal hypoxia that seemed to drive the deleterious effect on insulin sensitivity." (PMID 23951064, 2013). "Smoking more than 20 cigarettes per day is found to be associated with higher risk of MS in European and Asian populations because smoking could increase the risk of MS via the development of abdominal obesity and insulin resistance." (PMID 22590636, 2012). "This study uses a large existent cohort of patients and will generate valuable information as to the continuing effects of exercise specifically targeting cardiovascular function and disease risk, insulin metabolism, abdominal obesity, physical function, quality of life and psychological distress." (PMID 19951446, 2009). "The difference in total HEI-2015 scores between the insulin-taking group and the healthy group (β = −7.5 ± 2.4, p = 0.003) was not only statistically significant but also meaningful to health because the difference was large enough to reduce the risk of abdominal obesity." (PMID 39458437, 2024). "This condition, which is more accentuated in individuals with abdominal obesity, increases oxidative stress and mitochondrial dysfunction in muscle, the consequences of which are lipotoxicity and an increase in reactive oxygen species (ROS), causing insulin resistance and muscle inflammation." (PMID 36626317, 2023). "The possible mechanisms for the association between DII and general or abdominal obesity might be related to the effects of insulinogenic foods that cause reduced insulin sensitivity and higher insulin secretion, which can increase glucose uptake and lipogenesis." (PMID 37645243, 2023). "However, whether the change in CRF and/or abdominal obesity mediate the exercise-associated change in insulin sensitivity is unclear." (PMID 27936206, 2016). "In particular, abdominal obesity is correlated with an accumulation of visceral fat, which is associated with the secretion of adipokines that may have a detrimental metabolic effect and increase insulin levels." (PMID 19144203, 2009). "In light of these factors, the TyG index exhibits augmented predictive value for sarcopenia in populations with CKD and low prevalence of insulin therapy, where abdominal obesity is less pronounced." (PMID 41048435, 2025). "Some studies suggest that the interplay of pro‐inflammatory cytokines, oxidative stress and insulin resistance creates a bidirectional relationship between muscle weakness and abdominal obesity, which further impairs motor neuron function." (PMID 40162590, 2025). "The simultaneous elevation of TG and FBG, coupled with central obesity, is suggestive of potential mechanisms such as increased hepatic lipogenesis, reduced insulin sensitivity in adipose tissue, and impaired glucose uptake in peripheral tissues." (PMID 40863213, 2025). "To address the relationship between abdominal obesity and serum insulin levels, we utilized data from the KNHANES, which comprised 8886 men and 11,316 women." (PMID 41302993, 2025). "Cortisol, a hormone that significantly contributes to fat accumulation, particularly in the abdominal region, promotes insulin resistance, creating a feedback loop that contributes to abdominal obesity." (PMID 41341448, 2025). "Stratification by key clinical factors, including anti‐lipid drug use, central obesity, insulin use, and age group, revealed significant differences in survival outcomes." (PMID 41029007, 2025). "In Europe and the United States (U.S.), waist circumference (WC) has replaced serum insulin as a practical indicator of central obesity." (PMID 41302993, 2025).
Abdominal obesity (continued). "Central obesity-induced IR is characterized by impaired insulin function.It affects glucose uptake and hepatic glucose output.Overweight and morbid obesity impact insulin sensitivity." (PMID 41567335, 2025). "Chronic psychological stress increases cortisol levels, leading to central obesity and impaired insulin regulation." (PMID 40310144, 2025). "Chronic inflammation from central obesity reduces insulin sensitivity and disrupts the oral immune microenvironment, thereby worsening periodontitis severity." (PMID 41158658, 2025). "Supplementation improved ovarian morphology, menstrual regularity, insulin sensitivity, and reduced hirsutism, acne, and central obesity." (PMID 41497317, 2025). "The role of TNF-α as a promoter of central obesity results from its effects on lipolysis and the inhibition of insulin signalling in adipose tissue, leading to localized inflammation and enhanced fat accumulation." (PMID 40137151, 2025). "This review demonstrates that the role of miRs in regulating such mechanisms of AIMetS pathogenesis as oxidative stress, systemic inflammation, adipogenesis and central obesity development, and glucose and insulin metabolism has been the most studied." (PMID 40217882, 2025). "This protein is elevated in the blood serum of individuals with abdominal obesity, high triglyceride levels, and decreased insulin sensitivity." (PMID 39519343, 2024). "Stair climbing, a combination of aerobic and resistance exercise, has been shown to be effective in reducing abdominal obesity, lowering body weight and improving insulin resistance and lipid profiles." (PMID 39519409, 2024). "Anthropometric measurements like Waist (inch), Hip (inch) circumference, Waist-Hip Ratio, and Body Weight (Kg) play a key role in evaluating central obesity, a common feature of PCOS often associated with metabolic issues such as insulin resistance." (PMID 39492914, 2024). "Eight weeks of HFD consumption led to somatometric and metabolic changes, marked by increased body mass, central obesity, elevated plasma leptin and insulin levels, and a high HOMA–IR, reflecting key features associated with MetS." (PMID 39457000, 2024). "Even in the participants with central obesity, or further adjustment for the use of insulin, TC and TG, or for the substitution of waist circumference for BMI." (PMID 38308353, 2024). "A rare phenotype (node 8) with CRP ≤ 3 mg/L (mean: 1.4 (0.7; 2.7 mg/L)), presenting with central obesity (WHtR: 0.56 ± 0.04) and insulin resistance (FPI: 39.7 (29.2; 54.0 μIU/mL)) displayed the highest mean leukocyte counts." (PMID 38255379, 2024). "The study reveals that exercise mitigates MS by reversing high-fat diet-induced abdominal obesity, reducing lipid accumulation and inflammation, enhancing insulin sensitivity, and improving cardiovascular function." (PMID 39290329, 2024). "Cardiometabolic risk factors that are associated with CVD are blood pressure, body mass index (BMI), abdominal obesity, total fat mass, cholesterol, triglycerides, and insulin." (PMID 38791492, 2024). "Central obesity elevates circulating free fatty acids, impairing insulin signaling in muscles and liver." (PMID 39744182, 2024). "The impaired conversion of cortisone and cortisol has been reported as an important factor for insulin sensitivity and central obesity." (PMID 37122566, 2023). "Abdominal obesity is appreciated as a major player in insulin resistance and metabolically dysfunctional adipose tissue." (PMID 37807066, 2023). "Clofibrate treatment decreased central obesity and body weight and improved lipid profile and insulin sensitivity in MetS rats." (PMID 36982395, 2023). "Patients with central obesity are typically more insulin resistant and more likely to have NAFLD than those with lower-body obesity because the central obesity phenotype is linked to increased intra-abdominal fat." (PMID 37588314, 2023).
Abdominal obesity (continued). "Women with higher hs-CRP levels had worse metabolic risk profiles, including abdominal obesity, higher TG and lower HDL levels, and lower insulin sensitivity compared to women with lower hs-CRP levels." (PMID 37375693, 2023). "From our results, it would appear that insulin resistance has a greater role in determining carotid-radial stiffness than carotid-femoral stiffness, which, conversely, would be more influenced by central obesity." (PMID 37959384, 2023). "Abdominal obesity (AO) is prevalent in 38-88% ofPCOS patients, leading to insulin resistance by inhibiting insulin receptor tyrosinekinase in fat muscles (Oróstica etal., 2016)." (PMID 37962969, 2023). "The insulin sensitizer pioglitazone alone significantly improved depressive symptoms in MDD patients with abdominal obesity after 12 weeks of treatment." (PMID 37008928, 2023). "HL activity is normally higher in males than females and is elevated in abdominal obesity and hyperglycemic and insulin-resistant states." (PMID 37404855, 2023). "Other findings indicate that PPAR-γ is involved in metabolic processes, such as abdominal obesity, insulin sensitivity, and lipid metabolism." (PMID 36947700, 2023). "Abdominal obesity in PCOS patients seems to be co-responsible for the development of hyperandrogenism due to the insulin-mediated overstimulation of ovarian steroidogenesis." (PMID 37892519, 2023). "In whole, this set of data supports that early and long-term exposure to a high-sucrose diet induces MetS, mainly characterized by central obesity, disturbance of the glucose–insulin axis, and peripheral as well as hepatic IR." (PMID 35883886, 2022). "Previously, it has been reported that abdominal obesity and hyperandrogenism are linked to the dyslipidaemia in PCOS, and higher serum testosterone has been shown to be adversely associated with insulin levels and HOMA IR in such patients." (PMID 35455702, 2022). "A previous study suggested that adolescents with PCOS are severely insulin resistant, compared with a control group matched for body composition and abdominal obesity." (PMID 35646110, 2022). "The rise in lipolysis-derived NEFA contributes to the deleterious effect of abdominal obesity on insulin sensitivity in skeletal muscle and liver, including elevation in de novo lipogenesis." (PMID 36009446, 2022). "Patients with DM1 present clinical evidence of metabolic alterations, namely increased levels of triacylglycerol and low-density lipoprotein, increased insulin and glucose levels, increased abdominal obesity, and low levels of high-density lipoprotein." (PMID 33673200, 2021). "Based on the review of all seven RCTs selected, we found that the researchers demonstrated the effects of Vit D on three main components of MetS, which are BP, abdominal obesity, and insulin and glucose metabolism." (PMID 34589329, 2021). "The review of seven additional randomized clinical trials (RCT)-based studies suggest that Vit D supplementation has significant effects on BP, abdominal obesity, and insulin and glucose metabolism." (PMID 34589329, 2021). "South Asian people, for example, are more insulin resistant and more prone to abdominal obesity and low muscle mass than other ethnic groups." (PMID 33574565, 2021). "Clinical trials have depicted that administration of testosterone at physiological concentrations improved insulin sensitivity, central obesity, and heart failure progression in men suffering from metabolic disorders." (PMID 33546773, 2021). "Additionally, central obesity is associated with increased adipokines, insulin and reduced levels of adiponectin, which in turn, may increase the formation of reactive oxygen species and facilitate cellular lipid peroxidation and DNA oxidative damage, promoting hepatocarcinogenesis." (PMID 34620113, 2021).
Abdominal obesity (continued). "In a multivariable analysis adjusted for the year of study, age, and gender, prominent factors associated with increased IR or subclinical inflammation were abdominal obesity, glycated haemoglobin, and fasting insulin levels." (PMID 32566678, 2020). "Physical activity in the early post-menopausal years reduces abdominal obesity, but insulin sensitivity of adipose tissue seems unaffected by both menopausal status and physical activity." (PMID 33345051, 2020). "As for the CDK5 tv2 levels, these also correlated strongly with serum insulin levels, and moreover with the presence of central obesity in the T2D group (p < 0.05)." (PMID 30728419, 2019). "In a similar vein, the conicity index (CI), an index of abdominal obesity, has been considered useful for detecting central obesity, and has been studied as a predictor for alterations in fasting insulin, blood pressure, and triglyceride levels." (PMID 31344803, 2019). "Given the design of the present investigation, the sequence and timing of the fiber, abdominal obesity, and insulin resistance relationships cannot be determined." (PMID 29461482, 2018). "Abdominal obesity results in an inefficiency of serum insulin to manifest its effects of carbohydrate and fat metabolism." (PMID 30755836, 2018). "The main effects of central obesity were observed on insulin (Wald chi square = 17.4, P < 0.001), chemerin (Wald chi square = 4.7, P = 0.031), IL-6 (Wald chi square = 7.6, P = 0.001), and PAI-1 (Wald chi square = 5.9, P = 0.016)." (PMID 30114249, 2018). "Women tend to have peripheral fat distribution by contrast to central obesity with visceral fat accumulation in men, resulting in improved insulin sensitivity even at greater levels of weight gain." (PMID 28797259, 2017). "In this sense, whereas low-AGE diets can increase insulin sensitivity, high-AGE diets are related with increased fat intake and higher risk of abdominal obesity." (PMID 28915840, 2017). "Higher levels of BMI and parameters associated with glucose metabolism (the post-load glucose, insulin and HOMA-IR) were also found in abdominal obesity." (PMID 28421328, 2017). "HFD-rats developed central obesity and insulin sensitivity was reduced as evidenced by the marked reduction in insulin-induced phosphorylation of Akt in both cardiac and gastrocnemius muscle." (PMID 28399917, 2017). "In type 2 diabetic patients with abdominal obesity, glucose levels increased between 0.5 and 2 h, in concomitance with the increase in insulin and HOMA-IR." (PMID 28814963, 2017). "It has been reported that central obesity is one of the main characteristics of MetS, particularly due to increased values of free fatty acids in the blood and the inhibition of insulin action in peripheral tissues." (PMID 28264459, 2017). "It is well established that in older adults, chronic exercise is associated with improvement in insulin sensitivity and CRF as well as a reduction in abdominal obesity." (PMID 27936206, 2016). "It was found that the glucose uptake rate by insulin stimulating was negatively correlated with abdominal fat content in adipose tissue of patients with abdominal obesity." (PMID 27242533, 2016). "Mexican-American young adults with abdominal obesity had a higher odds of albuminuria even among those with normal blood pressure, normal glucose, and normal insulin sensitivity [adjusted odds ratio 4.5; 95% confidence interval (1.6–12.2), p = 0.004]." (PMID 27224643, 2016). "In contrast, the main mechanism of central obesity promoting TNBC progression is the disturbance of the ‘insulin-leptin-adiponectin’ axis." (PMID 27247890, 2016). "T2D, on the other hand is characterized by resistance to insulin action in tissues like liver, skeletal muscle and adipose tissue, which leads to other features such as dyslipidaemia and central obesity." (PMID 26300908, 2015).
Abdominal obesity (continued). "HFD-fed rats developed central obesity and insulin sensitivity was reduced as evidenced by the marked reduction in insulin-induced phosphorylation of Akt in both cardiac and gastrocnemius muscle." (PMID 26576929, 2015). "When hyperinsulinaemia is already present, the hypoglycaemics, high dose insulin and insulin secreteagogues, sulphonylureas, can have the adverse effects, worsening other aspects of MetS, such as central obesity." (PMID 25708599, 2014). "In our study, 75% subjects with poorly controlled glycemia had abdominal obesity with large dosage of insulin." (PMID 24650537, 2014). "Our current and previously reported findings suggest that the rs6717858 near GRB14 has a female-specific effect on insulin as well as on central obesity and lipids." (PMID 23754948, 2013). "Previous research also found that, relative to a control group, individuals who skip breakfast were more likely to be overweight or have abdominal obesity, elevated blood pressure, elevated total serum cholesterol or elevated serum insulin." (PMID 24093334, 2013). "In young overweight and obese subjects, AOPPs positively correlate with central obesity, triglycerides, and insulin, and negatively correlate with glucose to insulin ratio and HDL-cholesterol, suggesting an increased metabolic risk in this population." (PMID 23698776, 2013). "In patients with abdominal obesity, the NEAT score was significantly and negatively associated with serum insulin levels." (PMID 23711224, 2013). "An animal study showed that rats fed with fat rich in lipophilic POPs (primarily consisting of DDT, DDE, and PCBs) developed abdominal obesity and insulin insensitivity." (PMID 23131992, 2013). "They found a significant increase in body weight, body mass index, abdominal obesity, fasting glucose, insulin, and homeostasis model assessment over the 5-year follow-up among homozygotes for the rare BclI allele." (PMID 23282070, 2012). "Several defects of platelet function have been identified in insulin-resistant states and central obesity, as recently reviewed." (PMID 24278711, 2012). "Firstly, Asian populations, especially those of SEAR descent, are more prone to abdominal obesity and low muscle mass with increased insulin resistance." (PMID 22998969, 2012). "It has been previously observed that abdominal obesity is associated with reduced HDL-C and Low Density Lipoprotein Cholesterol (LDL-C) size, increased LDL-C number, triglyceride, and insulin resistance." (PMID 24533211, 2012). "Routine physical activity has been shown to improve abdominal obesity and weight control, glucose homeostasis and insulin sensitivity, coronary blood flow and reduces blood pressure." (PMID 22368754, 2012). "For women, the odds of abdominal obesity increased with diastolic blood pressure and insulin resistance." (PMID 21159215, 2011). "As a major finding the G-allele (risk-allele) of rs2605100 in LYPLAL1 associated with elevated concentrations of fasting serum triglycerides and fasting serum insulin and with estimates of central obesity." (PMID 21674055, 2011). "Decreased AMPK activity has been found in visceral adipose tissue of patients with central obesity due to Cushing's syndrome and of obese insulin-resistant individuals." (PMID 21774820, 2011). "It is therefore important to develop criteria for central obesity that can identify insulin resistant youth so that preventive measures can be taken before they develop complications of this condition." (PMID 21134291, 2010). "In vivo, chronic exposure to low doses of POPs commonly found in food chains induced severe impairment of whole-body insulin action and contributed to the development of abdominal obesity and hepatosteatosis." (PMID 20064776, 2010). "Male gender, younger age, higher waist circumference; as an indicator of central obesity, as well as non insulin use are independent predictors of elevated liver transaminase levels." (PMID 20103955, 2010).